TNF (tumor necrosis factor)
Diseases named in the same sentence as TNF in open-access papers (continued):
Sharing a sentence is not in itself a finding about the gene and the disease.
ulcerative colitis (continued). "TNF-α is a pro-inflammatory mediator associated with ulcerative colitis that is expressed at high levels in the colonic mucosa of patients with ulcerative colitis and has been the target of anti-TNF-α agents in human trials." (PMID 29959357, 2018). "The authors found a strong association only with TNF-α -308 polymorphism and ulcerative colitis-associated CRC both at the genotype and allele levels when compared with ulcerative colitis that did not progress to CRC as controls." (PMID 26572151, 2016). "We recently developed a mouse model of IBD that phenotypically and histologically resembles human childhood-onset ulcerative colitis (UC), using mice that are genetically modified to be deficient in the cytokines TNF and IL-10 (“T/I” mice)." (PMID 27045690, 2016). "Exhibited a significant therapeutic effect in mice with ulcerative colitis, reducing body weight loss by 4.6%, improving colon length and epithelial barrier protection, with a notable 60% reduction in inflammatory cytokines (TNF‐α and IL‐12)." (PMID 40384187, 2025). "As a result, this research utilized 11 serotonin derivatives to assess the effect of NO on LPS-stimulated RAW 264.7 cells and its role in regulating crucial cytokines linked to ulcerative colitis, specifically IL-6, TNF-α, IL-1β, and IL-10, through Griess and RT-qPCR assays." (PMID 40649400, 2025). "Furthermore, studies have reported that TNF-α promotes intestinal inflammation, and its upregulation is associated with increased ulcerative colitis (UC) severity." (PMID 40428786, 2025). "Additionally, elevated expression of IFNG-AS1 has been associated with activation of IFN-γ, IL-1, IL-6, and TNF-α in ulcerative colitis specimens." (PMID 40658679, 2025). "Although literature suggests that resistance to TNF inhibitor (TNFi) therapy in patients with ulcerative colitis (UC) is partially linked to immune cell populations in the inflamed region, there is still substantial uncertainty underlying the relevant spatial context." (PMID 36662860, 2023). "In a pooled analysis of data from randomized trials assessing anti-TNF use, elderly people (≥60 years) with ulcerative colitis had a higher increased risk of serious adverse events, but this increase in risk could not be attributed to anti-TNF therapy." (PMID 37674503, 2023). "Increasing evidence indicates a genetic association between TNF-α and ulcerative colitis." (PMID 29694505, 2018). "In ulcerative colitis patients, TNF from T cells appeared to be an important driver of disease, while in graft versus host disease, both T cell and macrophage/monocyte-derived TNF cause gastrointestinal damage." (PMID 26765224, 2016). "Although vedolizumab, a gut-selective α4β7 integrin antagonist, is associated with a lower risk of systemic infections compared to anti-TNF agents, its localized impact on mucosal immunity may still predispose patients to enteric infections, particularly in ulcerative colitis." (PMID 41011540, 2025). "The present study aimed to explore the association of long noncoding RNAs (lncRNAs) with inflammation, disease activity, and predicting response to anti-tumor necrosis factor (TNF)-α therapy in patients with ulcerative colitis (UC)." (PMID 41769045, 2026). "Astragalus polysaccharide significantly alleviates colonic damage in ulcerative colitis by inhibiting pro-inflammatory factors (TNF-α, IL-6, IL-1β) and oxidative stress products (MDA) and restoring the activity of antioxidant enzymes (SOD)." (PMID 41395463, 2025). "Patients with ulcerative colitis received biological anti-TNF-α treatment with adalimumab, which led to an improvement in average disease activity in this group." (PMID 41226478, 2025). "Among patients with ulcerative colitis treated with vedolizumab or anti‐TNF therapies, Clostridium difficile infection (CDI) was documented in 43 cases, 11 of which were severe, with up to 33% experiencing recurrence." (PMID 40384187, 2025).
ulcerative colitis (continued). "Verified through in vivo and in vitro experiments, HZ demonstrated partial inhibition of the TLR4/NF‐κB signaling pathway, reduction in inflammatory factors IL‐6 and TNF, and the ability to suppress T cell differentiation and activation in ulcerative colitis." (PMID 41164267, 2025). "In parallel with current results, inhibition of iNOS in patients with ulcerative colitis decreased mucosal TNF-α and IL-6 production and promoted ulcer healing and positive prognosis." (PMID 40644360, 2025). "In rats with ulcerative colitis, low doses of PC administered orally for one week decreased the expression of TNF-α, IL-1β, and IL-6 and increased the level of transforming growth factor (TGF)-β, which is essential for healing of the intestinal mucosa." (PMID 40498951, 2025). "Among these, immune checkpoint inhibitor-related colitis (irAE colitis) presents with symptoms resembling ulcerative colitis, for which high-dose corticosteroids and anti-TNF-alpha antibodies are recommended." (PMID 41170268, 2025). "In conclusion, this study provides the first evidence that ceAF can mitigate ulcerative colitis (UC) and TNF-α-induced inflammatory responses by inhibiting the LCK/ZAP70/LAT signaling pathway, thereby reducing TCR signaling hyperactivation." (PMID 39857385, 2025). "Patients with ulcerative colitis often receive therapies that reduce inflammation, such as anti‐tumour necrosis factor alpha (anti‐TNFα) therapies." (PMID 40721990, 2025). "Similar inhibitory effects on NF-κB, IL-6, and TNF-α have been observed in Dextran Sodium Sulfate (DSS)-induced ulcerative colitis models." (PMID 40869259, 2025). "Secondly, we demonstrate that the level of this local TNF-α expression is a powerful molecular indicator that strongly correlates with both the objective endoscopic severity of Ulcerative Colitis and the histological grade evaluation." (PMID 41374327, 2025). "In a related study on a DSS-induced ulcerative colitis (UC) model, inhibition of the mTOR axis significantly reduced the expression of TNF-α, IL-1β, and iNOS, leading to improved conditions." (PMID 40077417, 2025). "Ulcerative colitis (UC) is a chronic inflammatory condition requiring lifelong management, with anti‐tumor necrosis factor α (anti‐TNF‐α) agents often used for refractory cases." (PMID 40313140, 2025). "In this six-month study of 23 patients with ulcerative colitis (UC) treated with TNF alpha inhibitor biologics, 60% of patients achieved clinical remission." (PMID 40871445, 2025). "Our findings are also in line with previous immunohistochemical studies that demonstrated strong TNF-α expression in colonic biopsies from patients with ulcerative colitis." (PMID 41374327, 2025). "A pilot study showed a decrease in serum levels of tumor necrosis factor‐alpha TNF‐α, interleukin IL‐6 and IL‐8 in ulcerative colitis patients in remission who received sprouted barley." (PMID 40432400, 2025). "We then compared the occurrence of these events among similar patients with ulcerative colitis who were exposed to other anti‐TNFα therapies." (PMID 40721990, 2025). "Golimumab (GLM), an anti‐tumour necrosis factor alpha (anti‐TNFα) agent, is indicated for moderate to severe ulcerative colitis (UC)." (PMID 40721990, 2025). "In conclusion, we validated RT-qPCR quantification of TNF-α from FFPE mucosal biopsies as a reliable surrogate for fresh tissue analysis in ulcerative colitis." (PMID 41374327, 2025). "This shift reduces pro-inflammatory cytokines (TNF-α, IL-1β, IL-6), elevates anti-inflammatory IL-10, and mitigates mucosal damage, positioning miR-223 as a potent therapeutic candidate for ulcerative colitis (UC)." (PMID 40799643, 2025). "The inhibitory effect of CP on TNF-α was previously demonstrated in a murine model of peritonitis and ulcerative colitis, in which CP doses of 40 mg/kg reduced IFN-γ, IL-6, and TNF-α levels." (PMID 40142455, 2025).
ulcerative colitis (continued). "Recent reviews have confirmed that persistent TNF-α overexpression not only triggers but also maintains chronic inflammation in ulcerative colitis by disrupting epithelial barrier integrity and amplifying mucosal immune responses." (PMID 40428786, 2025). "TNF-α is recognized as a pro-inflammatory cytokine involved in the development of ulcerative colitis." (PMID 40438415, 2025). "Golimumab is an anti‐TNFα therapy that was approved to treat patients with moderate to severe ulcerative colitis in 2013." (PMID 40721990, 2025). "Previously, TNF-a producing CD14dimCD16+ monocyte apheresis has been performed in Ulcerative colitis patients." (PMID 38899253, 2024). "The observed results indicate a beneficial effect of the implemented anti-TNF-α treatment in patients with ulcerative colitis." (PMID 39407507, 2024). "Some strains belonging to the genus Paraclostridium have been shown to worsen pathogenesis by increasing TNF‐α, IL‐16, IL‐1, and IL‐17 expressions in the mouse‐induced ulcerative colitis model." (PMID 39620016, 2024). "We evaluated the efficacy of add-on submucosal injections of GUT-1, the RNA oligonucleotide inhibitor of CHST15, to ongoing anti-tumor necrosis factor (TNF) antibody treatment in patients with moderate-to-severe ulcerative colitis (UC)." (PMID 38664814, 2024). "Among ulcerative colitis (UC) patients, the persistence rates were 35% for anti-TNF and 75% for UST, with UST again showing greater persistence as indicated by KM analysis (log-rank p = 0.036) and Cox regression (HR: 0.28, 95% CI: 0.08–0.996, p = 0.049)." (PMID 39741232, 2024). "The therapeutic landscape for ulcerative colitis (UC) has recently broadened to include anti-TNFα, anti-integrin, and anti-IL-12/23p40 antibody agents." (PMID 39425179, 2024). "In a rat model of ulcerative colitis, the authors found that intervention with Quercus brantii gel significantly improved inflammatory markers such as TNF‐α, and IL‐6." (PMID 39479683, 2024). "Studies have shown that tumor necrosis factor-α (TNF-α)-secreting cells increase in inflamed intestinal mucosa, and in patients with ulcerative colitis, interleukin 8 (IL-8) is diffusely expressed throughout the mucosa." (PMID 39770669, 2024). "COST decreased the expression of IL1- β, IL-6, and TNF-α in a murine model of acute ulcerative colitis, according to another study." (PMID 38629103, 2024). "Akkermansia muciniphila can also improve DSS-induced ulcerative colitis by regulating some key inflammatory response components, including TNF-α, IL-6 and other pro-inflammatory cytokines." (PMID 39452928, 2024). "Here, we report that EF-hand domain-containing protein D2 (EFHD2), highly expressed in normal intestine tissues but decreased in intestinal biopsy samples of ulcerative colitis patients, protects intestinal epithelium from TNF-induced IEC apoptosis." (PMID 38346956, 2024). "The keywords “anti-TNF,” “infliximab,” “adalimumab,” “biologic-naïve,” “first line,” and “ulcerative colitis,” were used during the electronic search." (PMID 38835557, 2024). "Excessive production of nitric oxide in ulcerative colitis as observed in CCG is due to increased activation of inducible nitric oxide synthase (iNOS) that is activated by pro-inflammatory cytokines such as TNF-α." (PMID 38476652, 2024). "PI3K/AKT activation increases the production of the proinflammatory cytokine TNF-α, exacerbating inflammation and promoting the transition from ulcerative colitis (UC) to colorectal cancer (CAC)." (PMID 38892375, 2024). "The classic TCM formulaSi-Wu decoction significantly decreases the levels of IL-6, TNF-α, and IL-1β, effectively treating ulcerative colitis." (PMID 38379418, 2024). "The therapeutic efficacy of TNF-α-neutralizing antibodies in the treatment of ulcerative colitis, as demonstrated in both clinical and preclinical studies, further highlights its central role." (PMID 39410232, 2024).
ulcerative colitis (continued). "In ulcerative colitis [UC] first-line vedolizumab [VDZ] demonstrated superior effectiveness over 5 years compared to anti-tumour necrosis factor [anti-TNF] agents [p = 0.006]." (PMID 38041850, 2024). "Cyclosporine A, tacrolimus and the anti-TNF antibody infliximab have constituted the mainstay of therapy in the treatment of acute severe ulcerative colitis once steroids have failed." (PMID 37358998, 2023). "In chronic inflammatory conditions such as ulcerative colitis, T. erecta has shown effectiveness by reducing TNF-α and IL-6 levels." (PMID 38139287, 2023). "Human intestinal organoids, which are originated from ulcerative colitis (UC) patients, were exposed to pro-inflammatory cytokines (INFγ + TNFα) to induce intestinal inflammation, or coexposed to cytokines and PJ34." (PMID 37108260, 2023). "COST reduced the inflammatory response in mice with ulcerative colitis by lowering the proinflammatory cytokines IL-1β, IL-6, and TNF-α." (PMID 37736519, 2023). "At present, treatment of mild to moderate ulcerative colitis involves, primarily, 5-aminosalicylates, while thiopurines or biological agents (anti-tumor necrosis factor alpha or anti-integrin therapy) are used for moderate to severe disease." (PMID 36445533, 2023). "The immunosuppressive effects of treatment for ulcerative colitis (UC), including chronic corticosteroids, anti‐TNF agents, and JAK inhibitors, can impact the spread of latent or obscure infections." (PMID 37207089, 2023). "Nonetheless, others have found that TNFα is an important mediator in the pathogenesis of ulcerative colitis, and it is also involved in increased neuronal excitability in dorsal root ganglia innervating the colon." (PMID 37049400, 2023). "Previous studies have shown that TNFα and IL6 increase in patients with ulcerative colitis, and deletion of TNFα or IL16 reduces CAC in murine models." (PMID 37810110, 2023). "TNF-α regulates the NF-κB pathway by promoting IκBα degradation, NF-κB p65 phosphorylation and NF-κB nuclear transfer, which aggravates the injury of ulcerative colitis." (PMID 37006260, 2023). "In ulcerative colitis, probiotics reduced the inflammatory factor TNF-α by inhibiting TLR4 expression in colonic tissue." (PMID 37138630, 2023). "In conclusion, ulcerative colitis with high metabolism and low malignancy showed a higher degree of benefit from monoclonal antibody drug therapy against TNF-α." (PMID 36445533, 2023). "Ulcerative colitis tissue atlas reveals evidence of sex-dependent differences in inflammation and TNF inhibitor resistance." (PMID 36662860, 2023). "The key factors involved in the inflammatory cascade during ulcerative colitis are cytokines, such as tumor necrosis factor-α (TNF-α), interferon-γ (IFN-γ), interleukin (IL) -2, IL-6, IL-8, which are also linked to chemokines and adhesion molecules." (PMID 36834520, 2023). "More importantly, treatments using anti-TNFα have shown to be effective early on but less effective in inducing remission in ulcerative colitis cases." (PMID 37049400, 2023). "Recently, treatment with LAB-fermented whey protein showed immunomodulatory effects by reducing the expression of IL-4 and TNF-α in an ulcerative colitis mouse model, demonstrating the potential of LAB-fermented proteins as novel immune-regulating therapies." (PMID 38062113, 2023). "Adalimumab is a blocker of tumor necrosis factor (TNF)-alpha with established efficacy in the treatment of ulcerative colitis." (PMID 36846641, 2023). "In animal models of hepatocytic and aortic inflammation and ulcerative colitis, FA treatment inhibited the production of the inflammatory cytokines IL-6, IL-1, and TNF-α." (PMID 37371967, 2023). "Thirty-five were men (67%), 52% had ulcerative colitis, 60% received thiopurines, and 38% an anti-TNF drug before lymphoma diagnosis." (PMID 36765708, 2023).
ulcerative colitis (continued). "Cavidine improved ulcerative colitis by regulating the oxidation and antioxidant balance and inhibiting NF-κB signaling pathways and pro-inflammatory cytokines, such as TNF-α and IL-6, in colonic tissue." (PMID 35631773, 2022). "Our study also further confirmed the important role of inflammatory factors, such as NO, TNF-α, IL-1β and IL-6, in the occurrence and development of ulcerative colitis." (PMID 35163182, 2022). "Taken together, Sildenafil treatment suppressed acetic acid-induced ulcerative colitis, probably via inhibiting NF-κB/TNF-α signaling dependent of Nrf-2/HO-1 pathway, reducing oxidative stress and attenuating inflammation." (PMID 35834151, 2022). "Previous studies in ulcerative colitis have demonstrated that blocking IL-1R2 upregulated the expression of pro-inflammatory chemokines induced by Il-1β, such as TNF-a, IL-6 and IFN-γ." (PMID 35087030, 2022). "From an anti-inflammatory perspective, lycopene was able to reduce the following inflammatory biomarkers: TNF-α, IL-1β, and IL-6 in the acetic acid-induced ulcerative colitis rat model." (PMID 35990343, 2022). "Of note, the majority of studies included both CD and ulcerative colitis (UC) patients, and patients on concomitant TNF-α inhibitors, which impedes meaningful analysis of drug efficacy." (PMID 35907797, 2022). "Anthocyanin-rich bilberry extract was found to lower the levels of proinflammatory cytokines IFN-γ and TNF while increasing the levels of Th17 cell-specific cytokine IL-22 and immunoregulatory cytokine IL-10 in ulcerative colitis patients." (PMID 35204188, 2022). "For example, changes in the TNF-α concentration in patients with ulcerative colitis are correlated with changes in intestinal flora." (PMID 35739900, 2022). "In patients with active ulcerative colitis, IL-8 and TNF-α mRNA levels were significantly higher than those in the controls." (PMID 35844499, 2022). "Prospective pilot study in 15 patients with active ulcerative colitis and previous failure to anti-TNFα starting vedolizumab treatment." (PMID 35783609, 2022). "Phosphatidylcholine (PC) also showed anti-inflammatory properties against TNF-α induced inflammation in ulcerative colitis." (PMID 35909558, 2022). "The inflammatory response affects the formation of ulcerative colitis and increases the production of proinflammatory cytokines such as TNF-α, IL-1β, IL-6, and IFN-γ11,40." (PMID 35894303, 2022). "For ulcerative colitis, the most used CoTs were vedolizumab plus anti-TNF and vedolizumab plus tofacitinib." (PMID 35207347, 2022). "According to some authors, BMI is a reliable predictor of anti-TNF medication failure in patients with ulcerative colitis." (PMID 36232469, 2022). "In line with the present work, GSK-3β was reported to be activated in ulcerative colitis, where it positively regulated NF-κB, which then controls pro-inflammatory mediators like TNF-α." (PMID 36386153, 2022). "The CXP was programmed to extract TNFα-native active ulcerative colitis (UC) patients from EMRs using defined International Classification of Disease-10 (ICD-10) codes." (PMID 35173908, 2022). "Due to this controversy, this study aimed to appraise the short-term anti-TNF (adalimumab [ADA]) relics on cardiac function by gauging the echocardiography indexes in patients with immunosuppressant refractory ulcerative colitis (UC)." (PMID 36687438, 2022). "TNF-α, in contrast, plays a major role in ulcerative colitis, whereas NETs sustain inflammatory signals, and neutrophils have also been reported to show increased viability." (PMID 35242132, 2022). "In this review, we summarized the current understanding of using mucosal TNF transcript (TNF) to improve the precision of anti-TNF biological therapy strategies in patients with ulcerative colitis (UC)." (PMID 35663996, 2022). "A certain number of patients with ulcerative colitis (UC) are refractory to anti-TNF-α antibodies; biomarkers are thus needed to predict treatment efficacy." (PMID 36078882, 2022).